CD4 (CD4 molecule)
Diseases named in the same sentence as CD4 in open-access papers (continued):
Sharing a sentence is not in itself a finding about the gene and the disease.
Autoimmunity (continued). "Moreover, in further studies, we will investigate the fine-tune mechanisms of bystander-activated CD4+ T cells during the development of autoimmune neuroinflammation, including their interactions with myeloid cells, neuronal cells, etc." (PMID 30755603, 2019). "As a consequence, the expansion of the CD4+ FOXP3+ Tregs due to elevated IL-2 concentrations likely reflects an attempted compensatory mechanism to regulate Teff cell hyperactivity in an inflammatory environment during these periods of flaring autoimmunity." (PMID 31781109, 2019). "This expansion of antigen-specific B cells during CNS autoimmunity could amplify cognate interactions between dysregulated B and CD4 T cells, which in turn could independently drive neuro-inflammation and relapses at later stages of MS." (PMID 29944721, 2018). "Such a reduction in CD4 T cells might also dysregulate autoimmunity in HTLV-1 carriers or HAM/TSP patients." (PMID 29212930, 2018). "CD4+ T cells were defined as main drivers of heart-specific autoimmunity in myocarditis." (PMID 30035131, 2018). "In our study, four patients with low CD4/CD8 ratios exhibited autoimmunity." (PMID 29849668, 2018). "In summary, Our results imply that CD4+CD127+3G11+ cells may be a type of positive Tregs which are different from conventional CD4+ Tregs which inhibit autoimmunity in vivo." (PMID 30483251, 2018). "For this, we first generated bone marrow (BM) chimera reconstituted with a 50:50 ratio of WT and IL-2−/− BM cells to avoid spontaneous T cell activation due to autoimmunity in IL-2−/− mice and 8 weeks later, naïve CD4+ T cells derived from WT and IL-2−/− BM were isolated from the chimeric mice." (PMID 30190718, 2018). "Our data suggest that IL-27-treated mature DCs may block autoimmunity through upregulation of CD4+CD127+3G11+ Tregs development in vivo." (PMID 30483251, 2018). "Previous studies showed that CD4+ Tregs is a negative regulator of autoimmunity." (PMID 30483251, 2018). "In conclusion, autophagy is increased mainly in CD4+ T lymphocytes from salivary glands, suggesting that the survival of these cells might initiate autoimmunity and could play a key role in pSS pathogenesis." (PMID 28743286, 2017). "IFN-γ also plays a role in regulation of autoimmunity that is mediated by CD4+CD25+ Treg." (PMID 28878770, 2017). "In addition, abnormal neurofibromin production suppresses Fas ligand expression, therefore preventing the apoptosis of CD4+ T cells, which is important for the development of autoimmunity." (PMID 28552839, 2017). "We reasoned that the observed relative preservation of the regulatory T-cell compartment, including maintenance of naïve regulatory CD4 T-cells, may contribute to limit the emergence of autoimmunity upon thymectomy." (PMID 28686710, 2017). "Autoimmune disorders such as Sjögren’s syndrome substantially target the lacrimal gland, wherein autoantigens are expressed on the surface of the epithelial cells, leading to the retention of CD4 and CD8." (PMID 28661456, 2017). "Thus, a cascade of events produces autoimmune inflammation and tissue destruction in the eye following infiltration by activated CD4+ T cells." (PMID 29079770, 2017). "CD4+ T cells play a central role in orchestrating protective immunity and autoimmunity." (PMID 29238350, 2017). "We have previously shown that the CD4-driven fatal autoimmunity seen in Foxp3-deficient mice is abrogated in the absence of OX40 and CD30, whereas CD8 immunity was preserved." (PMID 28646041, 2017). "One long-term goal of the islet transplantation and autoimmunity field is to either deplete “indirect” autoreactive CD4 T cells or re-educate these CD4 T cells to become Foxp3+ regulatory CD4 T cells, while also generating additional “indirect” Tregs specific for transplant-derived antigens." (PMID 29259578, 2017).
Autoimmunity (continued). "An epigenetically altered CD4+CD28+ T cell subset, caused at least in part by nitration of T cell signaling molecules, is found in patients with active lupus, and nitrated T cells are sufficient to cause lupus-like autoimmunity in animal models." (PMID 28620656, 2017). "Our work has shown that absence of OX40 and CD30 costimulatory signals prevents CD4 T cell–driven autoimmunity in Foxp3-deficient mice, suggesting a novel way to block these side effects." (PMID 28646041, 2017). "One question we are currently addressing is whether antigen from apoptotic cells can activate autoreactive CD4 T cells and whether this is sufficient to drive autoimmunity." (PMID 28257518, 2017). "Other subsets of CD4+ T cells, such as Th9, T follicular helper (Tfh), T follicular regulatory, and T regulatory 1 (Tr1), are also reported to contribute to the development of neuroinflammation and autoimmunity." (PMID 29238350, 2017). "The present study has identified 36 potential microbial CD4 T cell epitopes that might trigger autoimmunity due to their shared sequence and structural homology with human peptides." (PMID 29062305, 2017). "Therefore, in addition to PD-1, we analyzed the expression of the co-inhibitory receptors LAG-3 and Tim-3, which are known to play important roles in limiting autoimmunity, in CD4+ and CD8+ T cells." (PMID 28356069, 2017). "If CD4 T cells commit to a distinct helper lineage, they start to express certain transcription factors that determine their subsequent mode of action such as immunity, tolerance, autoimmunity, or allergy." (PMID 29312303, 2017). "Intriguingly, Foxp3+CD4 regulatory T cells may represent a path toward developing antigen-specific tolerance in both autoimmunity and transplant recognition." (PMID 29259578, 2017). "Also, CD8+ regulatory T cells are essential for CD4+CD25+ regulatory T cell functions in the suppression of autoimmunity." (PMID 27887663, 2016). "Their depletion might result in the organ-specific autoimmunity developing and autoimmunity diseases, and these changes could be prevented by CD4+CD25+ cells in the animal models." (PMID 27278520, 2016). "Alternatively, on-going infection, inflammation and/or autoimmunity could explain the high number of CD4+ T cells in the bone marrow of these wild caught bats." (PMID 27883085, 2016). "Activation of CD4+ T cells by presentation of β-cell antigens by APCs in the pancreas and the regional draining lymph nodes represents a first step in the initiation of autoimmunity, leading to organ inflammation and ultimately β-cell destruction." (PMID 26973647, 2016). "Irrespective of the presence or duration of autoimmunity all insulin-variants were superior in stimulating insulin-specific CD4+T-cell clones." (PMID 26975663, 2016). "In contrast, T cell-specific deletion of A20 protects from CD4+ T cell-mediated autoimmunity, which may be partially explained by increased cell death of activated A20-deficient CD4+ T cells due to caspase-independent and RIPK3-dependent necroptosis." (PMID 28004776, 2016). "Thus, the gut environment favours the generation of autoreactive CD4+ T cells with unique regulatory functions, potentially important for preventing CNS autoimmunity." (PMID 27198196, 2016). "However, a greater increase of SR CD4+ T cells was observed in the CNS of IL-27R−/− mice, indicating that Tr1 cells are also critical in limiting autoimmunity during chronic JHMV infection." (PMID 27708643, 2016). "CD4+ CD25+ Foxp3+ Treg is a critical sub-population of CD4+ T cells that is essential for maintaining self tolerance and preventing autoimmunity, for limiting chronic inflammatory diseases, such as asthma and inflammatory bowel disease and for regulating homeostatic lymphocyte expansion." (PMID 26884314, 2016).
Autoimmunity (continued). "In conclusion, MPLA-tDCs are able to modulate antigen-specific responses of both naive and memory CD4+ T cells and might be a promising strategy to “turn off” self-reactive CD4+ effector T cells in autoimmunity." (PMID 27698654, 2016). "While rebound Tregs are dysfunctional, DT-resistant Foxp3+ Tregs have been shown to protect against lethal autoimmunity and may thus suffice to control the SR CD4+ T cells during chronic JHMV infection." (PMID 27708643, 2016). "Thus, EAE data establish that calcitriol exerts protective biological effects against autoimmunity in vivo through the nuclear VDR in CD4+ T lymphocytes." (PMID 25852682, 2015). "In SLE, defects in IL-10 secretion permit pre-naïve B cells to promote CD4+ T-cell activation and may thereby enhance the development of autoimmunity." (PMID 26209442, 2015). "Replacement of physiological doses of IL-2 could restore self-tolerance and prevent further autoimmunity by enhancing the function of CD4+ T regulatory cells (Tregs) to limit the activation of auto reactive T effector cells (Teffs)." (PMID 26646829, 2015). "However, the role of CD4+CD25high T cells in autoimmunity and, in particular, in the pathogenesis of T1D, remains the subject of intensive investigation for the possible relevance of this subset in the development of innovative immunotherapeutic approaches." (PMID 26393578, 2015). "Thus, using genetic approach, we clearly demonstrated the significant impact of miR-31 expressed by CD4+ T cells on the development of autoimmunity." (PMID 26165721, 2015). "Although the pathogenic functions of Eomes+CD4+ T cells in autoimmunity have not been previously analysed, expression of Eomes is linked with cytotoxic function in CD8+ T cells and natural killer cells." (PMID 26436530, 2015). "Therefore, further studies are needed to better clarify the identity and role of CD4+Foxp3+CD25− cell population in autoimmunity." (PMID 26592184, 2015). "Primarily it was supposed that a subset of CD4+ T cells with a Th1 phenotype producing IFN-γ is critical in autoimmunity of MS, however it is now clear that IL-17 producing CD4+ T cells, known as Th17, are the main responsible cells for inflammation and pathogenesis of MS." (PMID 25938517, 2015). "The combined use of CTLA4Ig and anti‐ICOS mAb in our model was far superior in blocking primary CD4+ T‐cell responses, suggesting this dual targeting may have significantly enhanced clinical benefit in treating autoimmunity and graft rejection." (PMID 25754933, 2015). "However, the role of CD4+CD25high T cells in autoimmunity and their molecular mechanisms remain the subject of investigation." (PMID 26393578, 2015). "Therefore, understanding how effector and regulatory CD4 T cells listen to IL-2 will unveil pathways and targets to modulate CD4 T cell responses during infection, autoimmunity, and cancer." (PMID 25569154, 2015). "In addition to their classic roles of maintaining immunologic tolerance to self and preventing autoimmunity, CD4+ regulatory T cells can also inhibit immune responses against pathogens." (PMID 28210682, 2015). "Importantly, the 1C6 model will enable us to distinguish between the molecular pathogenesis of CD4+ versus CD8+ T cell-driven CNS autoimmunity." (PMID 26557120, 2015). "IL-5 promoted induction of antigen-specific CD4+CD25+ TReg cells that suppress autoimmunity." (PMID 27095999, 2015). "BH3 Tg mice are therefore expected to have increased numbers of autoreactive CD4 T cells, which as key mediators of autoimmunity, could be responsible for the acceleration of disease in these mice." (PMID 25182415, 2014). "However, this has been at the expense of CD4 driven autoimmunity that can have considerable morbidity and even mortality." (PMID 24782861, 2014).
Autoimmunity (continued). "One of the key questions remains whether CD4+CD25-Foxp3+ T cells actually represent a beneficial counter-mechanism against autoimmunity, or on the contrary, if these cells are part of the damaging auto-immunological machinery of SLE." (PMID 24774748, 2014). "CD11a overexpression in CD4+ T cells can induce major-histocompatibility-complex-specific T cell autoreactivity in vitro and autoimmunity in vivo, suggesting that the correlation of DNA hypomethylation and autoimmune diseases is due to the elevated level of CD11a." (PMID 25414732, 2014). "Post-activation cytokine production by CD4+ TEM cells are likely crucial in driving autoimmunity." (PMID 24968232, 2014). "Thus, mice that lack STAT-3 in CD4+ T cells are unable to generate Th17 cells and are resistant to animal models of autoimmunity." (PMID 25374443, 2014). "In Systemic Lupus Erythematosus (SLE), increased expression of miR-142-5p in CD4+T cells prevents autoimmunity while a downregulation may result in autoreactive T cells and hyperactive B cells." (PMID 25238588, 2014). "Complementary to its impact on CD4+ T-cell CNS autoimmunity, our findings further suggest that HGF treatment could be exploited to control CD8+ T-cell-mediated, MHC I-restricted autoimmune dysfunctions such as MS." (PMID 24344806, 2013). "Overall, the RIP-HA model offers unique opportunities to study mechanisms of antigen-specific suppression of β cell autoimmunity, employing cotransfer of TCR-HA+ Treg cells, either with a Foxp3+ or Foxp3− phenotype, together with pathogenic T effector cells (CD4+TCR-HA+ or CD8+CL4+)." (PMID 23691523, 2013). "CD4+CD25+ Treg cells have a central role in protecting an individual from autoimmunity." (PMID 24187560, 2013). "Transfer of these TR2-deficient CD4+ T cells to lymphopenic recipients resulted in colitis, but not overt autoimmunity." (PMID 24115907, 2013). "Th17 T cells: CD4+ T cells and γδ T cells that express T-helper 17 (Th17)-type cytokines, such as IL-17A, and mediate immune responses against bacterial and fungal infections, as well as autoimmunity." (PMID 23828644, 2013). "In addition, PMA/ionomycin activation of splenic cells revealed that Ly9-deficient mice foster CD4+ T, CD8+ T, and iNKT cells capable of secreting major quantities of IFN-γ prior to the development of autoimmunity." (PMID 23914190, 2013). "Abnormal production of neurofibromin suppresses expression of fas-ligand, preventing apoptosis of CD4+ T-cells, which may contribute to the development of autoimmunity." (PMID 23691379, 2013). "miRNAs miR-326 and miR-155 modulate T cell polarization and may contribute to CD4+T cell-mediated autoimmunity." (PMID 23346094, 2012). "Absence of CD4+CD25+FoxP3+ natural suppressor T cells has been shown to enhance the development of T cell-mediated autoimmunity, whereas adoptive transfer of these cells was associated with opposite effects." (PMID 22727044, 2012). "Moreover, IL-6 is involved in autoimmunity by altering the balance of Th17 cells by inducing the differentiation of Th17 cells from naïve CD4+ T cells." (PMID 23133751, 2012). "Th17 cells, a population of CD4+ T helper cells that secretes a set of proinflammatory cytokines including IL-17, is considered a distinct cell lineage that seems to antagonize Treg development and thus promote autoimmunity." (PMID 22428018, 2012). "The categorization of CD4+ T cells in Th1 and/or Th2 constitutes an oversimplification and it has been shown that regulatory T cells with CD4+CD25+ phenotype not only play a role in controlling autoimmunity but also have suppressive effects on immune responses." (PMID 22927872, 2012). "CD4+CD25+Foxp3+ regulatory T (Treg) cells inhibit autoimmunity and protect against tissue injury." (PMID 22591709, 2012). "This anti-apoptotic factor enhances the survival of CD4+ T cells and might be one explanation for autoimmunity in humans suffering from multiple sclerosis." (PMID 21843342, 2011).
Autoimmunity (continued). "CD25+ Tregs are a subset of CD4+ T cells with a critical role in the prevention of autoimmunity." (PMID 21858123, 2011). "Consequently, the findings of increased TCR signalling of naïve CD4 T-cells, without increased proliferation, in PPMS, and the increased homeostatic proliferation of naïve CD4 T-cells in RRMS favour the development of autoimmunity." (PMID 22096637, 2011). "The development of EAE was further retarded in mice that received 2 injections of CD8+ T cells from PCC-immunized mice as compared to control mice suggesting that continuous Vß-specific CD8+ T cell generation or maintenance is required for the suppression of CD4+ T cell-mediated autoimmunity." (PMID 21738737, 2011). "In autoimmunity, the failure to suppress CD4+CD25low T cells is important for disease development." (PMID 21151941, 2010). "However, the onset of autoimmunity was strictly dependent on the presence of HA-specific CD4+ T helper cells from HNT transgenic mice." (PMID 20856822, 2010). "The susceptibility of CD4+ CD25+ regulatory T cells to HIV infection and CD4 loss may both contribute to dysregulation of immune responses and favour autoimmunity." (PMID 19830165, 2009). "Notably, PB CD4+ cells exhibited the largest number of significantly elevated phospho-signaling effectors, underscoring the importance of these cells in autoimmunity." (PMID 19693272, 2009). "In particular, autoimmunity could contribute to impair CD4 T cell functions in HIV-1 infected persons via reactivity to the CD4 molecule itself." (PMID 19943950, 2009). "Several hypothetical defects in CD4+CD25high regulatory T cell function that could lead to autoimmunity have been proposed." (PMID 19046457, 2008). "It is notable that Pep-deficient mice fail to spontaneously develop overt autoimmunity, although they do develop large germinal centers, increased Ig concentrations, enhanced TCR-mediated signaling, and increased numbers of splenic CD4+ and CD8+ effector/memory T cells." (PMID 19578517, 2008). "Furthermore, reconstitution of CD4+CD25+ T cells in the transferred cell populations prevented the development of autoimmunity." (PMID 15606917, 2004). "Existing functional evidence suggests that this could be through the production of full length functional ERAP2 protein resulting in an enhanced response to infection and autoimmunity, or through the regulation of gene expression in CD4 + T cells, resulting in immune dysregulation." (PMID 41428259, 2025). "Regulatory CD4+ T cells (Treg) that express the lineage-specific transcription factor Forkhead box P3 (FoxP3) are essential for maintaining peripheral self-tolerance, thereby preventing and managing inflammation and autoimmunity throughout an individual’s lifespan." (PMID 40493320, 2025). "In contrast, co-transfer of these CD25+ CD4+ Treg cells could reduce or even prevent autoimmunity." (PMID 41366167, 2025). "Interestingly, reduced insulin sensitivity in CD4+ cells may protect against the immunosuppressive effects of insulin, preserving effector T cell activity and enhancing autoimmunity." (PMID 39768214, 2024). "Remarkably, 2 CD4+ T cell populations (clusters 2 and 3) significantly upregulated IL-21, a cytokine linked to type 1 diabetes and other autoimmune conditions but not yet to PNS autoimmunity." (PMID 39087473, 2024). "It is well documented that aldosterone can lead to increased polarization of CD4+ cells into proinflammatory subsets (Th17, Th1) and that the following aldosterone-mediated immune activation can play an elevated role in some diseases, e.g., autoimmunity and metabolic syndrome." (PMID 38254698, 2024). "However, the approach of one-size-fits-all cannot be applied to autoimmunity since some autoimmune diseases are characterized by immunoregulatory bystander T cells such as in the case of SLE where activated bystander CD4 T cells expressing NKG2D secrete IL-10 and TGF-β." (PMID 39669576, 2024).